TNF (tumor necrosis factor)
Diseases named in the same sentence as TNF in open-access papers (continued):
Sharing a sentence is not in itself a finding about the gene and the disease.
acute pancreatitis (163 papers, 2005 to 2025). An acute inflammatory process that leads to necrosis of the pancreatic parenchyma. "The onset of experimental acute pancreatitis causes an increase in TNF-α expression in the pancreas." (PMID 40150718, 2025). "We first investigated the association between TNF inhibitor use and acute pancreatitis across the entire population and duration of study." (PMID 39712842, 2024). "We studied the association between acute pancreatitis and TNF inhibitors IFX, ADA, GOL, CTZ, and ETN." (PMID 39712842, 2024). "One important possible explanatory factor for acute pancreatitis seen in association with TNF inhibitor therapy is the concomitant use of other drugs with strong associations with acute pancreatitis." (PMID 39712842, 2024). "In clinical reports on drug-induced acute pancreatitis associated with TNF inhibitor use, it is common to also report other risk factors for acute pancreatitis such as gallstones, hypertriglyceridemia, alcohol use, and serum immunoglobulin assays such as IgG4." (PMID 39712842, 2024). "The release of TNF-α is believed to have a significant role in causing systemic effects in acute pancreatitis." (PMID 39139157, 2024). "It reduced airway hyperreactivity induced by hepatic ischemia-reperfusion injury by decreasing TNF-α levels in tracheal tissue, and protected against acute pancreatitis-associated lung injury by inhibiting Ang II." (PMID 37064885, 2023). "Twenty pathways were directly or indirectly associated with acute pancreatitis, including the TNF signaling pathway and the PI3K-AKT signaling pathway." (PMID 37347002, 2022). "The effects of the infusion of ADSCs on the production of pro-inflammatory cytokines (IL-6 and TNF-α) linked to acute pancreatitis were examined." (PMID 35597800, 2022). "So far, some cross-sectional studies have shown that serum levels of IL6 and TNF-a are elevated after acute pancreatitis and are associated with chronic hyperglycemia after pancreatitis (CHAP)." (PMID 35498402, 2022). "Following acute pancreatitis, levels of triglycerides, leptin and tumor necrosis factor-α (TNFα) and biliary origin are associated with fatty pancreas." (PMID 35327494, 2022). "These additional tests are useful for excluding cases of acute pancreatitis that can be attributed to causes other than TNF inhibitors, such as gallstone pancreatitis, pancreatitis secondary to hypertriglyceridemia, alcoholic pancreatitis, and autoimmune pancreatitis." (PMID 39712842, 2024). "Following up on numerous case reports reporting drug-induced acute pancreatitis associated with TNF inhibitors, we conducted a systematic investigation of the adverse drug reaction relationship between the TNF inhibitors IFX, ADA, GOL, CTZ, and ETN and pancreatitis." (PMID 39712842, 2024). "Both TNFα and IL-6 are implicated in the regulation of apoptotic and necrotic pathways, influencing the balance between cell survival and death in the pancreas during acute pancreatitis." (PMID 38927047, 2024). "Interestingly, all the cytokines acting in acute pancreatitis are also found as a cause of the desmoplastic reaction, namely tumor necrosis factor (TNF), platelet activating factor, IL-1, IL-6, IL-8, and IL-10 as the main players." (PMID 35626089, 2022). "Given previous studies showing that CVB3 can cause acute pancreatitis in humans and mice, and that TNF-α and IL-6 are implicated in the development of this disease, it is likely that cytokines are also involved in virus-induced inhibition of cell proliferation." (PMID 33556114, 2021). "In particular, the proinflammatory cytokine, TNF-α, may play a central role in acute pancreatitis and mediate the systemic damage caused by the disease." (PMID 34830195, 2021). "Besides, in a mice model of acute pancreatitis, low-methoxyl PEC was found to downregulate TNF-α, IL-1β and IL-6 mRNA levels in ileal and colonic tissue, leading to the recovery of acute pancreatitis-associated disorder of the intestinal barrier." (PMID 32276396, 2020).
acute pancreatitis (continued). "It has also been demonstrated that TNF-α inhibition lowers mortality and lessens the severity of experimental acute pancreatitis." (PMID 40150718, 2025). "IL-1β, TNF-α, and IL-10 levels in the acute pancreatitis group were significantly increased when compared to the control negative group." (PMID 38333760, 2024). "Studies have highlighted the crucial role of NF-κB activation in pancreatic acinar cells and the subsequent expression of IL-1β, IL-6, and TNF-α in the initiation and aggravation of acute pancreatitis through the recruitment of inflammatory cells." (PMID 38550755, 2024). "Ali and Madkour suggested that the tissue concentrations of TNF-α, IL-6, and IL-1β in the melatonin pretreatment group were significantly lower than in the L-arginine-induced acute pancreatitis group." (PMID 38333760, 2024). "It has been shown that both NF-κB and NF-κB-regulated IL-1β, IL-6, and TNF-α expressions are related to the onset and exacerbation of acute pancreatitis." (PMID 38333760, 2024). "In a rat model of liver injury associated with severe acute pancreatitis, the inhibitor AG490 of JAK2 effectively reduced the serum levels of TNF, IL-6, and IL-18 by blocking excessive JAK2 and STAT3 activation." (PMID 38543164, 2024). "It has been suggested that proinflammatory cytokines such as IL-1β, TNF-α, and IL-6 are local and systemic mediators and play a role in the occurrence of acute pancreatitis." (PMID 38333760, 2024). "It was reported that proinflammatory cytokines such as TNF-α and IL-6 levels significantly increased in acute pancreatitis." (PMID 38333760, 2024). "IL-1β and TNF-α levels in the melatonin-treated pancreatitis group were significantly lower than those of the acute pancreatitis group." (PMID 38333760, 2024). "Emerging evidence suggests that necroptosis and the related TNF pathway are the primary drivers of Fibrogenesis and acute pancreatitis in the course of NAFP." (PMID 38961451, 2024). "The severity of pancreatic pathological injuries in acute pancreatitis correlates significantly with the levels of infiltrated inflammatory cell-mediated cytokines, such as IL-1β, IL-6, and tumor necrosis factor-alpha (TNF-α)." (PMID 38550755, 2024). "It has been reported that the production of pro-inflammatory cytokines, including TNF-α, IL-1β and IL-6, is a vital player in the pathogenesis of acute pancreatitis." (PMID 35042436, 2022). "This study found that apoptosis, autophagy, ferroptosis, oxidative stress, PI3K-Akt, NF-κB, TNF, and other signaling pathways were abnormally regulated during acute pancreatitis." (PMID 36671463, 2022). "For instance, quercetin has been reported to downregulate the expression of IL-1β, IL-6, TNF-α, NF-κB, and other pro-inflammatory cytokines, alleviating acute pancreatitis." (PMID 39280954, 2022). "During acute pancreatitis, acinar cells interact with pancreatic macrophages via TNF-α, IL-1β, IL-6, and monocyte chemoattractant protein (MCP)-1 secretion, and promote the recruitment of peritoneal macrophages to pancreatic tissue." (PMID 35883885, 2022). "In a rat taurodeoxycholate-induced acute pancreatitis model, acute pancreatitis was observed along with mast cell activation and an increase in TNF-α level in the pancreas, although these were prevented by pretreatment with a mast cell stabilizer." (PMID 36289761, 2022). "Several researches have been linking the upregulation of MMP-9 by TNF—α expression, and the levels of these two mediators have been correlated with the severity of acute pancreatitis." (PMID 35041718, 2022). "FGF21 has recently been reported to relieve acute pancreatitis and alter the serum concentrations of interleukin (IL)-6 and tumor necrosis factor (TNF)-α in mice." (PMID 35408949, 2022). "Pyroptosis, the main mode of acinar cell death during acute pancreatitis (AP), can aggravate the inflammatory response by releasing cellular contents and inflammatory factors such as tumor necrosis factor alpha (TNF-α) and IL-1β." (PMID 33975598, 2021).
acute pancreatitis (continued). "Downregulating the expression of TNF-α can inhibit the release of inflammatory factors and plays a role in the treatment of acute pancreatitis." (PMID 34925503, 2021). "A clinical reported indicated that during the early acute pancreatitis stage, pancreatitis acinar cells always produced the cytokines such as tumor necrosis factor α (TNF-α) and interleukin-1β (IL-1β)." (PMID 33824873, 2021). "In the present study, a significant increase in TNF-α levels was observed in the placebo-treated acute pancreatitis model hamsters, but it was ameliorated by treatment with the chymase inhibitor." (PMID 34830195, 2021). "Rau and collaborators observed that the immunosuppressant tacrolimus inhibited the infiltration of neutrophils in rats via reduction of the expression of the mRNA for TNF-α and IL-1β in a model of acute pancreatitis induced by taurocholate." (PMID 34206998, 2021). "HBP is critical for pancreatic necrosis response in acute pancreatitis by increasing the infiltration of M1 macrophages and promoting the secretion of inflammatory factors, such as TNF-α, IL-6, IL-1β, which can be reduced by heparin." (PMID 34895060, 2021). "This study aimed to investigate the efficacy of selectively inhibiting the soluble form of TNF (solTNF) using the biologic XPro1595 in a mouse model of acute pancreatitis." (PMID 34049483, 2021). "In the rats with arginine-induced acute pancreatitis, lycopene treatment reduced tumor necrosis factor-α and myeloperoxidase activity, and down-regulated inducible nitric oxide synthase gene expression in pancreatic tissues." (PMID 33672594, 2021). "Increased TNF-α levels were observed in a rat acute pancreatitis model, and improvement in the survival rate was shown by TNF-α blockade using an anti-TNF-α neutral antibody." (PMID 34830195, 2021). "The massive production of cytokines such as TNF-α leads to necrosis of acinar cells and accelerates the occurrence of acute pancreatitis." (PMID 34925701, 2021). "In a rat taurodeoxycholate-induced acute pancreatitis model, activated mast cells and increased mRNA levels of tumor necrosis factor (TNF)-α were observed in the pancreas, but they were prevented by pretreatment with a mast cell stabilizer, cromolyn." (PMID 34830195, 2021). "In acute pancreatitis, pro-inflammatory cytokines such as Interleukin-1β (IL-1β), IL-6 and tumor necrosis factor-α (TNF-α) are primarily produced within the pancreas and subsequently within distant organs." (PMID 32471279, 2020). "Over-expression of miR-9 in bone marrow-derived mesenchymal stem cells is also known to diminish the levels of IL-6, IL-1β, and TNF-α in acute pancreatitis, highlighting the critical role of miR-9 up-regulation in inhibition of inflammatory responses." (PMID 32765295, 2020). "In general, tumor necrosis factor-α (TNF-α) has been reported to induce pancreatic apoptosis in acute pancreatitis, and the transcription factor (NF-κB) is also proved to participate in the regulation of apoptosis." (PMID 32928312, 2020). "This is supported by the reports that PCT level is more valuable indicator than TNF-α for predicting severity of acute pancreatitis, bacterial infection after bronchoscopy or in neutropenic febrile children with acute lymphoblastic leukemia." (PMID 33238906, 2020). "Macrophages are a major source of TNF‐α, IL‐1β, and IL‐6, and high serum levels of these cytokines are consistent with acute pancreatitis disease severity." (PMID 32638512, 2020). "In an acute pancreatitis rat model induced with L-arginine, lycopene administration significantly reduced inflammatory mediators such as TNF-α and downregulated iNOS expression." (PMID 32806545, 2020). "By activation of the Wnt/β-catenin signal, acute pancreatitis was significantly alleviated, as is evident by the down-regulated inflammatory factors including IL-6/10, TNF, and IL-1β." (PMID 35515912, 2019).
acute pancreatitis (continued). "Published reports show that IL-10 attenuates the inflammatory response and decreases TNF-α secretion in acute pancreatitis." (PMID 29497350, 2018). "Low TNF-alpha concentration in patients with severe acute pancreatitis predicts the development of MODS and fatal outcome in another study." (PMID 30455877, 2018). "Previous studies showed that the administration of the interleukin-1β receptor antagonist prevents a serum rise in interleukin-6 and TNF-α levels, and decreases the severity of acute pancreatitis." (PMID 28430136, 2017). "TNFα is a key role in severe acute pancreatitis, triggers expression of other inflammatory cytokines such as IL-1β and aggravates the tissue injury." (PMID 28441432, 2017). "Evidences suggest that proinflammatory cytokines, such as IL-1β, TNF-α, and IL-6, act as mediators of acute pancreatitis." (PMID 29068376, 2017). "Increase of circulating pro-inflammatory cytokines is an important feature of acute pancreatitis, so in this study serum levels of TNF-α and IL-6 were determined." (PMID 28300832, 2017). "In the present study, the expression level of TNFα increased in both circulation and intestinal tissue, which is in consistence with previous study suggesting that acute pancreatitis was marked with high circulatory concentrations of TNFα." (PMID 28441432, 2017). "Numerous studies indicate that TNF-α plays a pivotal role in the development of severe acute pancreatitis." (PMID 28665321, 2017). "TNFα, playing a dominating role in severe acute pancreatitis, can trigger expression of other inflammatory cytokines such as IL-1β and IL-6 and aggravates the tissue injury." (PMID 28441432, 2017). "As a consequence of acute pancreatitis, apart from hyperamylasemia, elevated production of pro-inflammatory cytokines such as TNF-α, interleukin (IL)-1β and IL-6 is often a distinctive pathological parameter." (PMID 26971398, 2016). "Increased TNFα levels correlated directly with increased cytokine expression and severity of acute pancreatitis in a mouse model of pancreatitis." (PMID 27798657, 2016). "The role of proinflammatory IL-6 in predicting severity of acute pancreatitis seems much more valuable than TNF-α." (PMID 26199633, 2015). "We also investigated the role of anti-RA drugs including steroid, disease modifying anti-rheumatic drugs (DMARDs), and Tumor Necrosis Factor (TNF)-blockers in the occurrence of acute pancreatitis in RA patients." (PMID 26262880, 2015). "TNF-α is a pro-inflammatory mediator that promotes the adhesion of leukocytes to the endothelium and plays a vital role in the pathogenesis of severe acute pancreatitis (SAP)." (PMID 23783408, 2013). "According to our proposed scheme, acinar cell stress in early stages of acute pancreatitis produces IL-33 and also other cytokines (e.g., TNF-α, IL-1β) that again stimulate acinar cells to release more IL-33." (PMID 23418608, 2013). "Peritoneal macrophages activation during acute pancreatitis was confirmed by the increased mRNA expression of TNFα and IL1β." (PMID 22870264, 2012). "The inhibitory effect of melatonin on proinflammatory cytokine production has been confirmed by marked reduction of the blood level of TNFα in the rats with acute pancreatitis pretreated with this indoleamine." (PMID 22606640, 2012). "As with IL-6, TNF-α represents a major determinant of the systemic progression and end-organ damage such as acute lung injury in acute pancreatitis." (PMID 23110041, 2012). "In blood samples supplemented with tumor necrosis factor, E. coli or S. aureus, phosphorylation levels of NFκB were lower and levels of p38 were higher in patients with acute pancreatitis than healthy subjects." (PMID 21087472, 2010). "Proinflammatory cytokines, such as tumour necrosis factor α (TNFα), play fundamental roles in the pathogenesis of acute pancreatitis (AP)." (PMID 20396411, 2010).
acute pancreatitis (continued). "The present study aimed to assess Interleukin-8 (IL-8), C-reactive protein, and tumor necrosis factor-α as prognosticators of a severe course of acute pancreatitis." (PMID 20130823, 2009). "In another study, serum matrix metalloproteinase 9 (MMP9) levelin severe acute pancreatitis was positively correlated with TNFα and CRP levels." (PMID 18670651, 2008). "The studies show that theserum levels of tumor necrosis factor α (TNFα), interleukin (IL)-1β, IL-6, and IL-8 aresignificantly increased in acute pancreatitis." (PMID 18670651, 2008). "Given the importance of TNF-α in the pathogenesis of acute pancreatitis, investigators have regarded blocking the action of this mediator as an attractive treatment option." (PMID 17450307, 2007). "Stimulation of production of either acute phase proteins and adhesion molecules or several inflammatory cytokines, including TNF-α, IL-1β and IL-6, occurs after NF-κB activation in acute pancreatitis." (PMID 15987389, 2005). "In the progression of acute pancreatitis, inflammatory factors such as IL-6 and TNF-α drive neutrophil aggregation and release extracellular traps (NETs), exacerbating tissue damage, while inducing lymphocyte apoptosis (especially CD4+ T cells), leading to immune suppression." (PMID 41141256, 2025). "Persistent activation of PSCs by cytokines during acute pancreatitis such as TNF-α, IL-1, IL-6, and IL-10, may be a factor involved in the progression from acute pancreatitis to chronic pancreatic injury and fibrosis." (PMID 39759120, 2025). "ROS produced by acute pancreatitis stimulate NF-κB, leading to excessive release of cytokines such as interleukin-1β (IL-1β), interleukin-2 (IL-2), interleukin-18 (IL-18), interleukin-6 (IL-6), and TNF-α." (PMID 40411704, 2025). "Thus, controlling for the use of AZA is an important consideration in the study of drug-induced acute pancreatitis due to TNF inhibitors." (PMID 39712842, 2024). "Furthermore, AP administration reduced the production of pancreatic TNF-α and IL-6 during cerulein-induced acute pancreatitis." (PMID 38911237, 2024). "Similarly, a study suggested that the levels of TNF-α, IL-1β, and IL-6 were increased in acute pancreatitis groups compared with the sham group." (PMID 38333760, 2024). "Also, it has been stated that proinflammatory cytokines (TNFα, IL-1β, and IL-6) were significantly reduced, whereas antiinflammatory cytokines (IL-10 and IL-4) were increased in animals with acute pancreatitis pretreated with melatonin." (PMID 38333760, 2024). "The TNF-α, IL-1β, and IL-10 increased significantly in rats of the pancreatitis group of this study compared to healthy rats, they are considered indicators for acute pancreatitis and this finding is consistent with the findings of other authors." (PMID 38333760, 2024). "IL-1β and TNF-α act locally and exacerbate acute pancreatitis." (PMID 38333760, 2024). "In addition, kynurenine, a metabolite of tryptophan, can reduce acute pancreatitis mortality by inhibiting the production of inflammatory factor TNF-α." (PMID 39202831, 2024). "Activation of pancreatic proteases and dysfunction of pancreatic microcirculation in acute pancreatitis stimulate granulocytes, macrophages, and vascular endothelial cells to release IL-6, TNF-α, and other cytokines that participate in the inflammatory response and immunoregulation." (PMID 35496266, 2022). "TNF- α and IL-10 are cytokines that have been well studied in acute pancreatitis." (PMID 35041718, 2022). "Lycopene showed protective effects against severe acute pancreatitis in rats through reducing ROS levels in pancreas and serum levels of damage-related molecular patterns (tumor necrosis factor-α, IL-6, macrophage inflammatory protein-1α, and monocyte chemotactic protein-1)." (PMID 33672594, 2021). "Besides, it also investigated the effect of XCHD on the generation of IL-6, IL-1β, and TNF-α in an LPS-induced acute pancreatitis model." (PMID 33824873, 2021).